MUC22 (mucin 22)
Synonyms: PBMUCL1
Tractability: Antibody: UniProt predicts a signal peptide or a membrane-spanning region.
Safety:
Unwanted effects reported when the protein is acted on. In parentheses: how it was acted on, where the effect was seen, and who reports it.
severe cutaneous adverse reactions (source: ClinPGx)
Gene: Protein-coding gene on chromosome 6 (31,010,474 to 31,035,402, forward strand). Ensembl gene ENSG00000261272.
Subcellular location: Membrane
Gene Ontology:
Cellular component: membrane
Genetic constraint (gnomAD): Loss-of-function variants: 23 observed, 38.75 expected, observed/expected ratio (o/e) 0.59, 90% interval 0.43 to 0.84. The upper end of that interval is the gene's LOEUF score, 0.84, which puts it in group 3 of 6, group 1 being the genes least tolerant of losing a copy. Missense variants: 1,913 observed, 2,064.8 expected, observed/expected ratio (o/e) 0.93, 90% interval 0.89 to 0.96. Synonymous variants: 761 observed, 798.24 expected, observed/expected ratio (o/e) 0.95, 90% interval 0.9 to 1.01.
Homologues: Orthologues: chimpanzee MUC22 (92% identical).
Diseases named in the same sentence as MUC22 in open-access papers:
MUC22 is named in the same sentence as 22 diseases in open-access papers, as found by Europe PMC text mining. Sharing a sentence is not in itself a finding about the gene and the disease. The quoted sentences say what the papers report.
asthma (3 papers, 2018 to 2022). "MUC22 polymorphisms have been associated with diffuse panbronchiolitis and asthma in Latinos." (PMID 36389712, 2022).
ankylosing spondylitis (2 papers, 2023 to 2024). An autoimmune chronic inflammatory disorder characterized by inflammation in the vertebral joints of the spine and sacroiliac joints. "The MUC22 SNP rs10947121 has been associated with ankylosing spondylitis, a type of arthritis that causes inflammation in the joints and ligaments of the spine, as well as peripheral joints like the knees, ankles, and hips." (PMID 38172662, 2024).
childhood asthma (1 paper, 2023). "MUC22 is upregulated or downregulated in lung adenocarcinoma and squamous cell carcinoma and is also seen in childhood asthma Expression." (PMID 36721228, 2023).
lung carcinoma (1 paper, 2023). "The co-localization of MUC22 and MUC21 in the mucin gene cluster on chromosome 6p21.3 suggests a link between these genes in lung cancer progression and heterogeneity." (PMID 37858248, 2023).
multiple sclerosis (1 paper, 2024). A progressive autoimmune disorder affecting the central nervous system resulting in demyelination. "Finally, an association between MUC22 SNP rs3094672 and the autoimmune disorder multiple sclerosis has been shown, albeit with a protective role." (PMID 38172662, 2024).
cancer (1 paper, 2021). A tumor composed of atypical neoplastic, often pleomorphic cells that invade other tissues. "For MUC12, MUC17, MUC20 and MUC22, no statistical differences between cancer samples and normal controls were observed." (PMID 34828282, 2021).
epithelial carcinoma (1 paper, 2017). "A recent study of mucin expression in a human epithelial carcinoma cell line (A549) showed a strong induction of MUC8, MUC15, MUC20, MUC21, and MUC22 mediated by RSV infection." (PMID 29162850, 2017).
infection (1 paper, 2015). The state of being infected such as from the introduction of a foreign agent such as serum, vaccine, antigenic substance or organism. "Our data indicate that the MUC expression by RSV and hMPV differs significantly, as we observed a stronger induction of MUC8, MUC15, MUC20, MUC21, and MUC22 by RSV infection while the expression of MUC1, MUC2, and MUC5B was dominated by the infection with hMPV." (PMID 25977598, 2015).
MUC22 also shares sentences with these, for which no sentence is quoted: hyperthyroidism (2 papers); Arthritis (1); autoimmune disease (1); coeliac disease (1); COVID-19 (1); heart failure (1); lipoma (1); lung adenocarcinoma (1); major depressive disorder (1); malignant neoplasm of the thyroid gland (1); non-melanoma skin carcinoma (1); psoriasis (1); rheumatoid arthritis (1); squamous cell carcinoma (1).